BDNF (brain derived neurotrophic factor)
Diseases named in the same sentence as BDNF in open-access papers (continued):
Sharing a sentence is not in itself a finding about the gene and the disease.
depression (continued). "While these studies suggest a correlation between post-mortem epigenetic modifications at BDNF promoters, it is unclear how these differences relate to functional differences in BDNF transcription which underlie depression or suicide behavior in vivo." (PMID 23847551, 2013). "In our study Val allele has a higher distribution in the Chinese population, and Val/Val genotype or carrying Val allele of BDNF Val66Met polymorphism is associated with higher response to depression." (PMID 24274373, 2013). "Following chronic communal nesting increased BDNF levels in association with reduced neurogenesis and increased depression-like behavior have been also found in CD-1 mice." (PMID 22474604, 2012). "Despite well-established findings of lower serum BDNF in a depressed population, inferences of BDNF as a causal marker for depression are still limited." (PMID 21247257, 2012). "It should be noted that not only the hippocampus is implicated in the pathophysiology of depression as BDNF protein is increased in the frontal cortex of rats after treatment with different monoaminergic antidepressants." (PMID 22581450, 2012). "BDNF genotype also seems to be a risk factor for developing depression, in this case, specifically in men." (PMID 23170235, 2012). "Brain derived neurotrophic factor (BDNF) has been implicated in the pathophysiology of depression as well as neuropsychiatric and neurodegenerative disorders." (PMID 22768299, 2012). "Very recently, plasma BDNF was associated with response in the early course of treatment for depression." (PMID 22761741, 2012). "Neurotrophic tyrosine kinase receptor type 2 (NTRK2) and ligand brain-derived neurotrophic factor (BDNF) are the subject of intense investigation in psychiatry and have been associated with anxiety, suicide, and depression, amongst other disorders." (PMID 22802923, 2012). "As experimental findings suggest that alterations in BDNF signalling are associated with depression-related behaviours in women only, generalization to men is questionable." (PMID 21247257, 2012). "Our results show that plasma BDNF levels are associated with clinical outcomes during the treatment of depression." (PMID 22761741, 2012). "BDNF plasma and serum levels have been associated with depression, Alzheimer's disease, and other psychiatric and neurodegenerative disorders." (PMID 22523577, 2012). "An association between BDNF serum levels and severity of depressive symptoms has also been identified in two studies of patients with depressive disorder, although one other study reported a negative result." (PMID 21247257, 2012). "Both basic and clinical evidence indicates that depression is associated withseveral structural and neurochemical changes where the levels of neurotrophins, particularly of brain-derived neurotrophic factor (BDNF), are altered." (PMID 22654714, 2011). "BDNF is also associated to the pathology of depression and is thought to be a key target in the treatment of major depression." (PMID 21785720, 2011). "Another matter of discussion is the correlation with the gender of the individual, occurrence of a BDNF polymorphism and risk for developing depression." (PMID 22654714, 2011). "Repeated CORT treatment resulted in a graded increase in depression-like behaviour and impaired spatial learning that is associated with decreased hippocampal cell proliferation and BDNF levels." (PMID 21935393, 2011). "Disruption in BDNF function has been implicated in the pathophysiology of psychiatric disorders such as depression, and most treatments against anxiety are associated with the action of BDNF and its receptor." (PMID 22163304, 2011). "In what concerns to stress, a prominent cause of depression, it is well established its relation with low levels of BDNF expression." (PMID 22654714, 2011).
depression (continued). "A genetic link has been identified between BDNF variants and response of humans to anti-depressants and lower BDNF expression was associated with the development of major depressive disorder." (PMID 21306618, 2011). "As a conclusion, there is some clinical evidence for an important effect of the genetic variability in BDNF and serotonin transporter genes on the risk to develop depressive behaviours and depression-associated mood disorders, such as suicide." (PMID 22654714, 2011). "The brain-derived neurotrophic factor (BDNF) is associated with many psychiatric disorders such as depression and anxiety by participating in differentiation, growth and maintenance of neuronal cells." (PMID 21124898, 2010). "Depression is clearly associated with synaptic plasticity changes, resulting in decreased BDNF function, among other biochemical alterations." (PMID 21194425, 2010). "The BDNF 66M allele has been associated with depression in elderly subjects and is associated with reduced hippocampal volume." (PMID 20808944, 2010). "It has been described that depression is associated with decreased expression of neurotrophic factors, such as BDNF." (PMID 21194425, 2010). "Despite these observations, a possible causative relationship between BDNF function and the pathogenesis of depression or antidepressant efficacy requires further clarification." (PMID 20219105, 2010). "Recently we have reported that Ginkgo flavonols activate signaling pathways, which are heavily implicated in depression including the BDNF/pCREB pathway." (PMID 20226030, 2010). "A recent study showed that the mutation G196A (Val66Met) in the BDNF coding sequence, which is linked to impaired episodic memory and depression in humans, disrupts a recognition site in BDNF mRNA for the RNA-binding protein translin." (PMID 20507609, 2010). "Our depression model caused a sustained reduction in BDNF mRNA expression in hippocampus (up to 24 h)." (PMID 21194425, 2010). "On one hand decreased BDNF levels are associated with both human depression and “depressive-like behavior” in rodent models of the disorder." (PMID 21152205, 2009). "The most conserved NT among vertebrates is BDNF, and BDNF mutations correlate with epilepsy, anxiety, depression, attention deficit disorder, autism, and other cognitive and psychiatric disorders." (PMID 19018662, 2008). "Moreover, genetic variations in the BDNF gene have been linked to susceptibility to depression, further suggesting a causal role of BDNF dysregulation." (PMID 40855004, 2026). "The study's limitations include a small sample size of UC patients, the lack of analysis of gut microbiota composition and fecal butyrate levels, and the omission of key inflammatory cytokines such as IL-6 and TNF-α as well as some potential diagnostic biomarkers for depression such as BDNF." (PMID 40123849, 2025). "Moreover, the susceptibility of AYAC to conditions such as depression, anxiety, and substance use further predisposes them to elevated inflammatory cytokines and reduced BDNF, placing this population at heightened risk for prolonged CRCI." (PMID 40597835, 2025). "This raises the question regarding the necessity of classifying patients with depression into BDNF Met and non- BDNF Met subtypes, as the underlying mechanisms influencing CVD, such as MI, could differ between them." (PMID 41301929, 2025). "The monoamine hypothesis suggests that depression is caused by an imbalance of neurotransmitters such as norepinephrine and dopamine, and that reduced levels of BDNF may be one of the causes of the neurotransmitter imbalance." (PMID 40821018, 2025). "Dysregulation of BDNF has been implicated in depression and anxiety disorders." (PMID 40636047, 2025). "Numerous studies have suggested that depression is associated with reduced BDNF levels." (PMID 40281288, 2025).
depression (continued). "Imbalanced levels of BDNF are strongly linked to depression, and paeoniflorin may improve PPD by modulating BDNF and activating the mTOR signaling pathway." (PMID 41409594, 2025). "Interestingly, BDNF Val66Met polymorphism has been shown to have gender-specific associations with depression risk, suggesting potential individualized approaches to vitamin D intervention." (PMID 40497025, 2025). "The low levels of BDNF are associated with reduced synaptic plasticity and neuronal atrophy, which is consistent with the neurogenic hypothesis of depression." (PMID 40969945, 2025). "Furthermore, chronic stress suppresses the expression of BDNF, a protein crucial for neuronal survival, growth, and synaptic plasticity, and causes mood disorders such as depression." (PMID 40374544, 2025). "Novelty-seeking was associated with BDNF rs61888800 polymorphism in depression." (PMID 40002454, 2025). "Similarly, data from a cross-sectional study have shown that first-episode depression and recurrent depressive disorder are associated with lower serum concentrations of BDNF and higher IL-2 levels." (PMID 40133606, 2025). "Alterations in BDNF expression levels are closely linked to cognitive impairment in depression." (PMID 39819542, 2025). "In depression-related models, reduced acetylation at sites such as H3K9ac and H4K12ac has been associated with decreased expression of key mood-regulating genes, including brain-derived neurotrophic factor (BDNF) and the serotonin transporter (SLC6A4)." (PMID 41589304, 2025). "BDNF, a neurotrophin, and GSK3β, a versatile kinase, are key regulators implicated in depression." (PMID 40149774, 2025). "Studies indicate that elevated BDNF protein levels in the hippocampus may mitigate behaviors linked to depression." (PMID 40458804, 2025). "In summary, the investigation into the relationship between genetic factors, such as the BDNF Val66Met polymorphism, and psychiatric manifestations in MS could provide new insights into the underlying mechanisms of depression in this complex disease." (PMID 40003622, 2025). "In mood regulation, low BDNF levels are linked to depression and anxiety." (PMID 41234420, 2025). "Abnormalities in the brain’s Nrf2 and BDNF crosstalk might function synergistically to cause depression-like symptoms in rodents." (PMID 40149774, 2025). "Decreased BDNF has been repeatedly linked to depression, and inflammatory states such as COPD may suppress its expression." (PMID 40823578, 2025). "Moreover, ALLO is considered a potential therapeutic agent for mental disorders associated with HPA axis dysfunction and reduced BDNF levels, such as depression and anxiety disorders." (PMID 41155366, 2025). "Substantial research has linked lowered peripheral BDNF to decline in brain health and plasticity, in natural aging and Alzheimer’s disease, and also in stress-related mood disorders that involve neuronal atrophy, such as major depression and bipolar disorder." (PMID 39896238, 2025). "Notably, depression is often associated with hypercortisolism, which, along with oxidative stress, reduces brain-derived neurotrophic factor expression, leading to hippocampal atrophy." (PMID 39981405, 2025). "Since BDNF rs11030101 polymorphism belongs to the encoding region, it is estimated that it may affect depression or suicide attempts as an indirect association with rs6265 polymorphism, which is a close LD relationship, rather than a direct function." (PMID 41300755, 2025). "Reduced circulating BDNF is associated with the onset of several neurodegenerative diseases, including Alzheimer’s, Parkinson’s, Multiple Sclerosis, and Huntington’s disease, as well as psychiatric disorders such as major depressive disorder." (PMID 40697272, 2025). "Evidence has suggested that BDNF may reduce the risk of depression through a range of mechanisms, including enhancing neuroplasticity, promoting neurogenesis, and modulating neurotransmitters." (PMID 40821018, 2025).
depression (continued). "Furthermore, recent researches found that the mTOR/BDNF pathway in prefrontal cortex and hippocampus of mice is disrupted in depression and linked to impaired behavioral functions." (PMID 41234534, 2025). "Similarly, it is suggested that in mouse models of depression, the improvement of depression is associated with the modification of the BDNF/TrkB-GSK-3β signaling pathway." (PMID 40149774, 2025). "The signal may also be conveyed to the prefrontal cortex, hippocampus, and other areas to augment neuroplasticity (e.g., BDNF expression) and ameliorate neuronal damage linked to depression." (PMID 40843192, 2025). "Reduced BDNF level is associated with an increased risk of depression in patients with ACS." (PMID 41179812, 2025). "Interestingly, an ROC curve analysis including BDNF and IGF-1 offered an excellent diagnostic value for depression (AUC = 0.916, p < 0.0001), which was higher than BDNF or IGF-1 separately." (PMID 40141202, 2025). "The neurotrophic hypothesis of depression implicates BDNF deficiency as a key contributor to the disorder’s pathogenesis, particularly in relation to region-specific structural and functional brain changes." (PMID 40989841, 2025). "Butyrate stimulates BDNF secretion, a gene potentially associated with anxiety and depression." (PMID 41195402, 2025). "Additionally, other markers such as BDNF, kynurenine branch, inflammation, serotonin, dopamine, and norepinephrine have all been linked to depression, yet their involvement varies depending on depressive phenotypes." (PMID 40319044, 2025). "A large number of studies show that depression is associated with decreased BDNF production, which may indicate the importance of this neurotrophic factor in the etiology of depressive disorders." (PMID 40869303, 2025). "In addition, the pathogenesis of depression is linked to brain-derived neurotrophic factor (BDNF) signaling and impaired synaptic plasticity since BDNF, when associated with oxidative stress through interaction with ROS, triggers neuropsychological disorders." (PMID 39997749, 2025). "The neurotrophin hypothesis of depression posits that reduced hippocampal BDNF levels are strongly associated with stress-induced depressive states." (PMID 41440979, 2025). "Disruptions in BDNF signaling are linked to neurological diseases, such as major depression." (PMID 40458804, 2025). "Increased methylation of NR3C1 and BDNF genes is associated with increased risk of depression, suggesting that DNA methylation may play a role in the pathophysiology of the disorder." (PMID 41373485, 2025). "The BDNF gene has been associated with the underlying mechanisms of both depression and anxiety." (PMID 40806241, 2025). "According to the neurotrophic hypothesis, BDNF may contribute to the development of depression, because its low expression was associated with atrophy of the brain areas involved in emotion." (PMID 40655156, 2025). "Previous studies support “neurotrophic hypothesis of depression”, which suggests that reduced BDNF levels in the brain lead to atrophy and cell loss in depression, while antidepressants exert their therapeutic effects via increasing BDNF levels." (PMID 40598020, 2025). "Additionally, BDNF has been reported to be associated with heart failure, dementia, Parkinson's disease, and depression." (PMID 40242707, 2025). "Reduced BDNF levels, particularly in the brain regions involved in mood regulation, like the amygdala, prefrontal cortex, hippocampus, and amygdala, have been consistently linked to emotional stress and depression." (PMID 40282201, 2025). "BDNF is a neurotrophic factor involved in repairing brain damage and maintaining synaptic plasticity; after stroke, low BDNF levels are associated with poor long-term functional outcomes and depression, whereas rehabilitation significantly correlates with BDNF increase." (PMID 41447407, 2025). "BDNF is a biological marker associated with depression and CHD." (PMID 41179812, 2025).
depression (continued). "Moreover, genetic studies have shown that reduced BDNF expression, as well as deficits in glutamatergic and GABAergic signaling, are correlated with an increased risk of depression." (PMID 40453264, 2025). "Many sequelae of low physical activity, such as pro-inflammatory states or reduced BDNF expression, may increase depression risk progressively with duration and severity." (PMID 40443280, 2025). "Additionally, decreased BDNF concentrations are associated with other neuropsychiatric conditions like depression and schizophrenia." (PMID 40317574, 2025). "Moreover, improved physical health is linked to the increased release of brain-derived neurotrophic factor (BDNF), a contraction-induced myokine that is inversely associated with depression." (PMID 40075602, 2025). "Therefore, further in-depth studies are required to explore the role of the BDNF Val66Met polymorphism and its impact on thrombosis in patients with MI and depression." (PMID 41301929, 2025). "In addition, reduced BDNF is associated with depression, making BDNF a promising target for therapeutic intervention in mental stress-related disorders." (PMID 40771219, 2025). "However, genetic phospho-ablation at S1181 and S1201 in the mouse showed reduction in anxiety/depression-like phenotypes and increased axonal transport of BDNF, suggesting HTT function is associated with etiology of mood disorders and anxiety/depression in HD." (PMID 41303392, 2025). "Thus, additional population-based studies are necessary to explore the potential association between BDNF and depression." (PMID 40821018, 2025). "Consequently, therapeutic strategies aimed at restoring BDNF signalling are being explored as potential interventions for depression and associated neuropsychiatric disorders." (PMID 41226736, 2025). "However, recent studies have shown that stress, often cited as a cause of depression and anxiety, induces hippocampal atrophy and decreases brain-derived neurotrophic factor (BDNF)." (PMID 40806449, 2025). "Additionally, depression is associated with reduced levels of brain-derived neurotrophic factor (BDNF), which impairs neurogenesis and synaptic plasticity, further compromising cognitive processes." (PMID 40821017, 2025). "In addition, ketamine elevates extracellular glutamate levels in the PFC and HIP, while enhancing synaptic connectivity via activation of the BDNF-TrkB pathway, thereby mitigating the degenerative changes linked to depression." (PMID 40001468, 2025). "Furthermore, brain-derived neurotrophic factor (BDNF) is the most prominent neurotrophin associated with depression, playing a critical role in neural plasticity mechanisms." (PMID 40004979, 2025). "Low BDNF levels are associated with depression and anxiety, so the ability of butyrate-producing bacteria to increase BDNF expression may be one mechanism by which they exert and maintain antidepressant and anxiolytic effects in the OCG." (PMID 40871332, 2025). "Correlations between BDNF changes and improvements in depression and anhedonia supported the notion that biological markers like BDNF may underlie the mechanistic action of agomelatine on mood and hedonic capacity." (PMID 40129874, 2025). "Additionally, BDNF levels are associated with various psychiatric conditions, such as depression and anxiety, which are common in patients with AD." (PMID 41153486, 2025). "In contrast, little association between BDNF and depressive symptom improvement was found in a meta-analysis examining treatment-resistant depression patients receiving a wide range of treatments, including ECT, rTMS, VNS, ketamine, lamotrigine, riluzole, and atypical antipsychotics." (PMID 41440970, 2025). "While many pharmacological treatments for depression increase monoaminergic and BDNF signaling, they fail to address the other potential neurobiological contributors to depression, such as deficiencies in glutamatergic signaling and overactivity of the lateral habenula." (PMID 40453264, 2025).